DPP4 (dipeptidyl peptidase 4)
Diseases named in the same sentence as DPP4 in open-access papers (continued):
Sharing a sentence is not in itself a finding about the gene and the disease.
atherosclerosis (continued). "Furthermore, dipeptidyl peptidase 4 (DPP4) has an inflammatory role in the pathogenesis of atherosclerosis and ACS therefore, DPP4 inhibitors such as sitagliptin reduce the severity of ACS in diabetic patients." (PMID 36988260, 2023). "Whether circulating DPP4 is more active than its membrane-bound counterpart remains unclear, but DPP4 is increased locally in atherosclerosis with cell senescence and in vascular disease." (PMID 37097759, 2023). "This is further supported by previous findings stating that incretin antagonists, a GLP-1, and a glucose-dependent insulinotropic polypeptide, could partially attenuate the suppressive effects of DPP-4 inhibitors on atherosclerosis in diabetic mice." (PMID 36830597, 2023). "DPP4 protein levels and activity increase with atherosclerosis in mouse, monkey, and human." (PMID 37097759, 2023). "We next examined if hematopoietic cell derived DPP4 mediates atherosclerosis development." (PMID 36683148, 2023). "In this study, we demonstrated a critical role for DPP4 in both human and murine atherosclerosis." (PMID 36683148, 2023). "Importantly, DPP4 inhibition reduced senescent cell burden and coagulation and improved plaque stability, while single-cell resolution of senescent VSMCs reflected the senomorphic and senolytic effects of DPP4 inhibition in murine atherosclerosis." (PMID 37097759, 2023). "In vein endothelial cells, by inhibiting the GLP‐1R signalling pathway, DPP‐4 could also promote the development of atherosclerosis." (PMID 32713161, 2020). "In particular, oxidized low-density lipoprotein (oxLDL) regulates the expression of dipeptidyl dipeptidase IV (DPP4) in macrophages leading to the increase of CD36 + cells which are representative of the inflammatory processes of atherosclerosis in obese and insulin resistant patients." (PMID 33414766, 2020). "Animal studies suggested beneficial effects of DPP-4 inhibitors on atherosclerosis." (PMID 29773079, 2018). "The glucagon-like peptide-1 dependent and/or independent effect of DPP-4 inhibitors on the vascular wall may attribute to reduced atherosclerosis." (PMID 28250768, 2017). "Various studies suggest DPP4 inhibitors may also possess cardioprotective effect, including atherosclerosis." (PMID 28619058, 2017). "DPP-4 is an enzyme with substrates other than the incretin hormones, including cytokines that might influence inflammation and atherosclerosis." (PMID 28596642, 2017). "Because some studies over a longer period showed that DPP-4 inhibitors have an anti-atherosclerosis effect, the length of the study period may be a concern." (PMID 29017497, 2017). "Furthermore, the DPP-4 inhibitors des-fluoro-sitagliptin and alogliptin, have been reported to exert favorable effects in atherosclerosis." (PMID 29100378, 2017). "High activity of the DPP-4 enzyme in immune system might give a possibility of using dipeptidyl peptidase-4 inhibitors in anti-inflammatory therapy, particularly in atherosclerosis." (PMID 27413253, 2016). "We conducted a trial to evaluate whether DPP-4 inhibitors affect atherosclerosis in people with T2DM." (PMID 27351380, 2016). "In vivo studies added important knowledge about the action of gliptins on atherosclerosis and, interestingly, have suggested that DPP4 inhibition has GLP-1-independent effects, possibly through regulation of other enzyme substrates, acting on attenuation of endothelial dysfunction and atherogenesis." (PMID 26146634, 2015).
atherosclerosis (continued). "Besides the beneficial effects of DPP-4 inhibition on atherosclerosis, anti-atherosclerotic effects of GLP-1 supplementation were also demonstrated in animal models." (PMID 26251902, 2015). "Likewise, DPP-4 inhibitors including sitagliptin also reportedly inhibit atherosclerosis and inflammation in both GLP-1-dependent and -independent manners." (PMID 24607023, 2014). "In addition, we and others recently demonstrated that other kinds of DPP-4 inhibitors also reduce the plaque burden at the level of the aortic sinuses accompanied by macrophage infiltration in animal model of atherosclerosis." (PMID 24607023, 2014). "In addition to their antihyperglycemic effects, DPP-4 inhibitors promote post-injury regeneration of endothelium and myocardium and may inhibit the development of atherosclerosis." (PMID 38055184, 2024). "Thus, DPP4/Mid1, as a novel regulator of T‐cell motility, may be a potential inflammatory target in atherosclerosis." (PMID 36683148, 2023). "In addition, preclinical studies have suggested that DPP-4 inhibitors may have beneficial effects on atherosclerosis, through both GLP-1-dependent and -independent mechanisms." (PMID 37669959, 2023). "The actions of DPP4 mimic the atherogenic actions of hyperinsulinemia, and DPP4 inhibition in pro-atherosclerotic preclinical models resulted in a reduction of inflammatory and oxidative stress mechanisms, improved endothelial dysfunction, and reduced the development of atherosclerosis." (PMID 37298967, 2023). "DPP4 on the plasma membrane can be cleaved, releasing soluble DPP4 into circulation; therefore, we determined whether the serum levels of DPP4 changed in mouse models of atherosclerosis." (PMID 37097759, 2023). "No significant impact of DPP4 deficiency on T‐cell differentiation toward Th1 was observed, excluding differentiation defect as a cause for reduced Th1 in the atherosclerosis lesion of Dpp4T‐∆ mice." (PMID 36683148, 2023). "Thus, DPP4 could represent a key link between IR/Hyperin conditions and the development of atherosclerosis." (PMID 37298967, 2023). "DPP-4 inhibitor therapy has been shown to reduce the risk for atherosclerosis and CAD through both glycemic control and direct effects on the atherosclerotic process, including atherosclerosis or plaque stability, and this topic has been addressed in recent reviews." (PMID 29669555, 2018). "A previous study found that circulating DPP4 was elevated in type 2 diabetic patients, regardless of coronary artery disease status, which associated with subclinical left ventricular dysfunction and subclinical atherosclerosis in these patients." (PMID 28587613, 2017). "Previous experimental reports showing that DPP4 inhibition by genetic or pharmacological intervention alters vascular wall remodeling and atherosclerosis in mice led us to hypothesize that serine protease DPP4 plays an important role in the initiation and progression of atherosclerosis." (PMID 27654253, 2016). "On the other hand, oxLDL regulates the expression of dipeptidyl dipeptidase IV (DPP4) in macrophages, leading to an increase in CD36+ cells, which contributes to the inflammatory processes of atherosclerosis in obese and insulin-resistant patients." (PMID 39027472, 2024). "We found that Dpp4 was mainly expressed in cl.3 (CD4+ T lymphocytes) and was further increased in CD4+ T lymphocytes from patients with atherosclerosis." (PMID 36683148, 2023). "Consistent with single cell RNA sequencing results, DPP4+ (including both DPP4low and DPP4high) cells in CD4+ T‐cell population was significantly increased in patients with atherosclerosis." (PMID 36683148, 2023). "The single cell RNA sequencing data indicated that DPP4 was mainly expressed in cl.3 (CD4+ T cells) and was highly upregulated in CD4+ T cells in atherosclerosis." (PMID 36683148, 2023).
atherosclerosis (continued). "Adoptive transfer experiments in Rag1−/− mice using Dpp4+/+ and Dpp4−/− T cells demonstrated reduced atherosclerosis and attenuated CD4+ and CD8+ T‐cell infiltration in mice with Dpp4−/− T cells." (PMID 36683148, 2023). "Nesfatin-1, a novel adipokine and dipeptidyl peptidase-4 (DPP4), a mam malian serine protease, are potent factors of atherosclerosis." (PMID 34389003, 2021). "Indeed, DPP-4 inhibitors have been reported to possess protective effects on atherosclerosis in some animal models and in vitro experiments; however, some large clinical studies focusing on cardiovascular events could not verify the superiority of DPP-4 inhibitors." (PMID 27711199, 2016). "The immunomodulatory actions of DPP-4 inhibitors and GLP-1 analogs have already been discussed in general and for models of atherosclerosis." (PMID 26251902, 2015). "The following sections will focus on the antioxidant effects of DPP-4 inhibition and GLP-1 analog supplementation in atherosclerosis and sepsis." (PMID 26251902, 2015). "Thus, results of this study suggest that DPP-4/CD26 may play an important role in macrophage-mediated inflammation response and tissue remodeling since matrix metalloproteinases are crucially involved in atherosclerosis." (PMID 22973260, 2012). "Then, more recently, we found that a DPP-4 inhibitor, an enhancer of endogenous GLP-1 and GIP, prevented the development of atherosclerosis in the same animal model." (PMID 22536426, 2012). "Dipeptidyl peptidase-4 (DPP4) concentrations are known to correlate with nonalcoholic fatty liver (FL), which is also associated with subclinical atherosclerosis (SA)." (PMID 40249657, 2025). "Given its consistent elevation in atherosclerosis and the negative impact of DPP4 silencing on senescent cell viability, we sought to determine the role of DPP4 on the surface of senescent cells." (PMID 37097759, 2023). "Lack of DPP4 in hematopoietic cells or T cells reduces T‐cell infiltration and atherosclerotic plaque volume in atherosclerosis mouse models." (PMID 36683148, 2023). "Dipeptidyl peptidase-4 (DPP4) can influence lipid homeostasis and atherosclerosis progression." (PMID 34178021, 2021). "However, inhibitors of DPP4 have been shown in other studies to decrease SMC proliferation, resulting in decreased neointima formation and atherosclerosis." (PMID 31971988, 2020). "Recently, a study found that the balance between DPP4 and GLP-1 might be a therapeutic target for the management of vascular aging and atherosclerosis in animals." (PMID 32802136, 2020). "In spite of this, DPP inhibition including DPP-4 inhibition and DPP-8/9 inhibition may be a potential target for M2 polarization and atherosclerosis regression treatment." (PMID 30923552, 2019). "Also, some clinical studies have been published showing a potential effect on atherosclerosis and inflammation in patients with T2DM using DPP-4 inhibitors as compared to that in patients using other antidiabetic drugs or placebo." (PMID 28596642, 2017). "The results of the present study provide additional evidence to support the possible participation of DPP4 in atherosclerosis-based CAD with and without DM." (PMID 27654253, 2016). "Besides atherosclerosis, sepsis, and NASH, DPP-4 inhibitors and GLP-1 analogs exert immunomodulatory effects in various models of chronic inflammatory diseases such as colitis, asthma, chronic obstructive lung disease (COPD), and rheumatoid arthritis." (PMID 26251902, 2015). "Future studies and the use of cell-specific knock-out animals (DPP-4 and GLP-1 receptor) are needed to differentiate between the DPP-4- and GLP-1-dependent effects on vascular oxidative stress and inflammation in models of atherosclerosis." (PMID 26251902, 2015).
atherosclerosis (continued). "When we examined the in vitro effects of DPP-4/CD26 and its inhibitor on macrophage foam cell formation, an essential process of early atherosclerosis, DPP-4/CD26 showed no direct regulatory action on macrophage foam cell formation." (PMID 23967137, 2013). "Recently, several studies have shown that DPP-4 inhibitors and GLP-1R agonists exert also a potent anti-inflammatory effect and thus, may potentially contribute to the prevention of atherosclerosis." (PMID 22973260, 2012). "Many drugs, such as dipeptidyl peptidase 4 (DPP4) inhibitors, glucagon-like peptide-1 (GLP-1) receptor (GLP-1R) agonists, and sodium glucose cotransporter 2 (SGLT-2) inhibitors (SGLT-2i), also inhibit atherosclerosis development by reducing the proinflammatory response in EAT and PVAT." (PMID 40760703, 2025). "We also discovered a previously unrecognized pathway regulating T‐cell motility, which may provide a mechanistic basis for the role of DPP4 in atherosclerosis and raise the possibility of targeting the noncatalytic function of DPP4 as a therapeutic strategy." (PMID 36683148, 2023). "In addition to Dpp4, there was an upregulation of a number of inflammation‐related genes including Card8, Card16, Gzma, Prf1, Il2rg, Il32, Cd52, and Ccl4 in CD4+ T cells isolated from patients with atherosclerosis." (PMID 36683148, 2023). "Interestingly, DPP4 inhibitors have been proven effective at reducing atherosclerosis in mice independently of their canonical impact on glucose metabolism, suggesting that DPP4 has important functions in nonmetabolic tissues and cells." (PMID 37097759, 2023). "Randomized clinical trials would be necessary in non-diabetic individuals to test this hypothesis, since results from studies with DPP4 inhibitors in diabetics may not be relevant because that population often already has well established atherosclerosis." (PMID 32881912, 2020). "In T2DM, the activity of DPP4 seems to be increased and there are a growing number of in vitro and in vivo studies suggesting that this enzyme could be a new link between T2DM and atherosclerosis." (PMID 26146634, 2015). "The non-enzymatic function of DPP4 may also regulate inflammatory responses in immune system, and its inhibition may have a role in the treatment of inflammatory diseases such as atherosclerosis." (PMID 23359639, 2013). "Indeed, several experimental studies have revealed that incretin-based treatments, such as glucagon-like peptide-1 (GLP-1) receptor agonists and dipeptidyl peptidase-4 (DPP-4) inhibitors, significantly suppress the development of atherosclerosis in animal models." (PMID 22536426, 2012). "Besides, DPP-4 inhibitors were found reducing blood cholesterol levels and could downregulate the formation of atherosclerosis in both diabetic animal models and nondiabetic conditions." (PMID 30923552, 2019). "In addition, recent studies suggest that DPP-4 may play a direct role in vascular inflammation and atherosclerosis independent of its metabolic actions." (PMID 29402270, 2018). "Given that DPP-4 is identical to CD26, a cell surface glycoprotein with multiple functions in T cell activation, DNA synthesis, cell proliferation, and cytokine production, it was suggested that DPP-4 inhibitors might affect atherosclerosis by virtue of immune modulation." (PMID 25785279, 2015). "SAIS1 trial reported that treatments with DPP4 inhibitors have favorable effects on inflammatory mediators and oxidative stress in patients with T2DM without advanced atherosclerosis." (PMID 35763504, 2022). "This study showed that serum DPP-4 levels did not correlate with DPP-4 levels in SAT or EAT; the DPP-4 levels in the SAT correlated with the DPP-4 levels in the EAT, atherosclerosis, and FBG, and the DPP-4 levels in the EAT correlated with AF and eGFR." (PMID 35893426, 2022).
metabolic syndrome (83 papers, 2010 to 2025). A cluster of metabolic risk factors for CARDIOVASCULAR DISEASES and TYPE 2 DIABETES MELLITUS. "Differential methylation levels within the DPP4 promoter were found to be associated with DPP4 mRNA expression in VAT from obese women with metabolic syndrome." (PMID 36140405, 2022). "To summarize, we described a significant reduction in DPP4 activity following surgically induced weight loss which was associated both with an ameliorated dyslipidemia as was as an improvement in the liver marker GGT as an indicator for improved NAFLD/ NASH." (PMID 33538983, 2021). "It has also been reported that DPP-4 released from adipose tissue is positively correlated with an increasing risk score for the metabolic syndrome." (PMID 27652270, 2016). "Taken together, these data demonstrated that DPP4 is a new adipokine associated with increased visceral obesity, IR, and metabolic syndrome, which are all well-known risk factors for atherosclerotic disease." (PMID 26146634, 2015). "Because of this and because we were the first to describe DPP4 as a novel adipokine linked to parameters of the metabolic syndrome, we decided to develop an adipose tissue-specific KO mouse model." (PMID 26284071, 2015). "Some important enzymes whose inhibition could be related to the prevention of the metabolic syndrome and associated complications include pancreatic lipase, glucosidase, amylase, dipeptidyl peptidase 4 (DPP4), and others." (PMID 41134486, 2025). "Finally, rs17848915 (which was merged into rs17574) was found to be significantly associated with the methylation levels of DPP4 promoter region, which negatively correlates with abundance of its mRNA in severely obese women with metabolic syndrome." (PMID 35413090, 2022). "They reported that DPP-4 might be involved in the association between adipose tissue and metabolic syndrome." (PMID 35893426, 2022). "Dipeptidyl peptidase 4 (DPP-4) is a novel adipokine and may be involved in the association between adipose tissue and metabolic syndrome." (PMID 35893426, 2022). "The expression pattern of DPP4 is linked with dyslipidemia after the transplantation." (PMID 34298827, 2021). "The underlying mechanisms of DPP4 inhibitors in dyslipidemia remain exclusive." (PMID 34489872, 2021). "Accordingly, our study provides evidence that decreased DPP4 activity after weight loss surgery might contribute to the improvement in dyslipidemia." (PMID 33538983, 2021). "Thus far, only a few reports have described associations between some single-nucleotide polymorphisms of the DPP4 gene and dyslipidemia, including, triglyceride, TC, HDL-c, and LDL-c levels." (PMID 29556215, 2018). "DPP-4 inhibitors significantly lowered the risk of eGFR decline > 10% [hazard ratio (HR), 0.830; 95% CI, 0.715–0.964; P = 0.015], as well as the occurrence of dyslipidemia (HR, 0.834; 95% CI, 0.698–0.996; P = 0.045)." (PMID 29187821, 2017). "For GLP-1 analogues and DPP-4 inhibitors, a baseline assessment of pancreatic risk factors (e.g., triglyceride level, gallbladder status, alcohol use history) can be performed before initiating therapy, especially in patients with preexisting metabolic syndrome." (PMID 40308779, 2025). "We thus studied the prospective association of plasma DPP4 activity with the risk of incident metabolic syndrome and its components, as well as the predictive value of plasma DPP4 activity in identifying in individuals who will develop incident metabolic syndrome among healthy individuals." (PMID 24647445, 2014). "DPP4 is raised in the metabolic syndrome, and stimulates inflammation and proliferation in human vasculature." (PMID 40514620, 2025). "Recent research involving ZSF1 rats, a model of metabolic syndrome and ventricular stiffness, has demonstrated that the DPP-4 inhibitor linagliptin reduces LV stiffness by decreasing cardiac fibrosis and cardiomyocyte Fpassive." (PMID 40361188, 2025).